OTULIN (OTU deubiquitinase with linear linkage specificity)
Diseases named in the same sentence as OTULIN in open-access papers (continued):
Sharing a sentence is not in itself a finding about the gene and the disease.
skin inflammation (6 papers, 2019 to 2025). "Patients with reduced OTULIN expression due to autosomal recessive mutations develop fevers, dermatitis, and panniculitis." (PMID 32671059, 2020). "Here the authors show, using genetic mouse models and single-cell RNA-sequencing, that deficiency of OTULIN in keratinocytes causes skin inflammation and verrucous carcinoma via the induction of keratinocyte death, thereby implicating a function of OTULIN in keratinocyte homeostasis." (PMID 34625556, 2021). "Genetic deletion of Tnfr1, knockin expression of kinase-inactive Ripk1 or keratinocyte-specific deletion of Fadd and Mlkl completely rescues mice with OTULIN deficiency from dermatitis and tumorigenesis, thereby identifying keratinocyte cell death as the driving force for inflammation." (PMID 34625556, 2021). "Once OTULIN is ablated, it leads to the death of keratinocytes and subsequently to skin inflammation and verrucous carcinoma in mice." (PMID 41446873, 2025). "Of note, some OTULIN-mutant patients display signs of liver dysfunction and skin inflammation in the form of panniculitis and neutrophilic dermatosis." (PMID 35740456, 2022). "Together, these data demonstrate the development of a strong but delineated dermatitis in mice that lack OTULIN in keratinocytes, suggesting that proper regulation of LUBAC-mediated linear ubiquitination is needed in order to maintain skin homeostasis." (PMID 34625556, 2021). "Finally, we observed complete protection from dermatitis when ΔKerOTULIN mice were crossed onto a MyD88-deficient genetic background, suggesting that microbial components could be involved in driving dermatitis in OTULIN-deficient skin." (PMID 34625556, 2021). "In line with our observations, a study by the group of Manolis Pasparakis44, published in this issue of Nature Communications, describes similar findings, confirming the role of OTULIN in preventing skin inflammation by inhibiting the death of keratinocytes." (PMID 34625556, 2021). "For OTULIN, its mediated linear deubiquitination of proteins has been confirmed to be essential for maintaining skin homeostasis, preventing keratinocyte death, and suppressing skin inflammation." (PMID 41446873, 2025). "Thus, it can be concluded that the dynamic homeostasis of linear ubiquitination maintained by LUBAC and OTULIN is critical for preserving skin homeostasis and protecting against the development of dermatitis." (PMID 41446873, 2025). "In conclusion, we have shown that linear deubiquitination of proteins by OTULIN serves as a crucial biological mechanism important for the maintenance of skin stem cell homeostasis and the prevention of keratinocyte death and subsequent skin inflammation." (PMID 34625556, 2021). "Here, we show that mice lacking OTULIN selectively in keratinocytes exhibit a severe skin inflammation that presents on their tail skin and delineated regions of the back skin." (PMID 34625556, 2021). "Keratinocytes lacking OTULIN display a type-1 interferon and IL-1β response signature, and genetic or pharmacologic inhibition of these cytokines partially inhibits skin inflammation." (PMID 34625556, 2021). "OTULIN promotes rather than counteracts LUBAC activity by preventing its auto-ubiquitination with linear polyubiquitin, and OTULIN inhibits RIPK1-mediated keratinocyte necroptosis to prevent skin inflammation in mice." (PMID 37813853, 2023).
Immunodeficiency (3 papers, 2017 to 2024). Failure of the immune system to protect the body adequately from infection, due to the absence or insufficiency of some component process or substance. "This disease is mechanistically linked to mutations in the OTULIN gene, resulting in an immune disorder that compromises the body’s ability to effectively combat pathogens and foreign stimuli." (PMID 38774872, 2024). "Germline mutations of OTULIN cause various complex clinical phenotypes, including autoinflammatory disorders and immunodeficient disorders." (PMID 38774872, 2024). "It is noteworthy that patients with LUBAC-inactivating germline mutations, such as those with HOIL-1, HOIP and OTULIN mutations, suffer from immunodeficiency and autoinflammation." (PMID 30254289, 2018). "In contrast to patients with the LUBAC deficiency, OTULIN-deficient patients have no obvious immunodeficiency, although some of them suffered from iatrogenic infections induced by immunosuppressive therapies." (PMID 28469620, 2017). "In immune diseases, A20 and OTULIN might be new therapeutic targets for development of immunomodulatory drugs that can potentially increase or stabilize their expression." (PMID 28469620, 2017).
liver disease (3 papers, 2020 to 2022). "Our discovery that OTULIN deficiency also causes severe liver disease in humans and mice expands the range of pathologies associated with OTULIN and highlights the critical importance of proper regulation of M1-polyUb signalling." (PMID 32231246, 2020). "In an ORAS patient, OTULIN deficiency caused spontaneous and progressive steatotic liver disease at 10–13 months of age." (PMID 32231246, 2020). "To examine if OTULIN deficiency led to mTOR-driven liver disease, we tested if inhibition of mTOR could reduce the pathology in the Otulin∆hep mice." (PMID 32231246, 2020). "We provide evidence that OTULIN is a crucial in vivo regulator of liver homoeostasis in mice and humans, identify mTOR signalling as a surprising driver of liver disease in OTULIN-deficient mice, and show that mTOR inhibition with rapamycin can improve liver pathology caused by OTULIN deficiency." (PMID 32231246, 2020). "We and others recently showed that selective ablation of OTULIN in hepatocytes (OTULINLPC-KO) results in severe liver disease characterized by fibrotic and neoplastic responses." (PMID 34625556, 2021). "This liver pathology was fully penetrant in all Otulin∆hep mice, and we therefore conclude that OTULIN is intrinsically important in hepatocytes for preventing severe liver disease." (PMID 32231246, 2020). "In addition, one ORAS patient was identified to suffer from progressive steatotic liver disease suggesting that OTULIN is crucial for liver homeostasis." (PMID 35170849, 2022). "In this study, we identify OTULIN as critical for preventing liver disease in mice and humans." (PMID 32231246, 2020). "Here, we show that OTULIN prevents development of liver disease in mice and humans." (PMID 32231246, 2020). "Collectively, our findings show that OTULIN is required for maintenance of liver homoeostasis in mice and suggest that ORAS patients may develop liver disease in addition to the inflammatory manifestations." (PMID 32231246, 2020).
staphylococcal infection (3 papers, 2022 to 2024). An infection caused by Staphylococcus. "However, individuals with OTULIN haploinsufficiency are particularly susceptible to life-threatening staphylococcal infections." (PMID 38774872, 2024).
Stroke (3 papers, 2024 to 2026). Sudden impairment of blood flow to a part of the brain due to occlusion or rupture of an artery to the brain. "OTULIN is expected to become a key regulator in the pathophysiological process of heart failure-related stroke (Ref." (PMID 38525836, 2024). "Interaction analysis showed a significant interaction between HOIP and OTULIN on stroke severity." (PMID 42245667, 2026). "OTU deubiquitinase with linear linkage specificity (OTULIN) was identified as a regulator in the pathogenesis of heart failure-related stroke through the intersection analysis of heart failure-related chip data and stroke-related chip data." (PMID 38525836, 2024).
Cerebral ischemia (2 papers, 2018 to 2024). Restriction of arterial blood supply to the brain associated with insufficient oxygenation to support the metabolic requirements of the tissue. "Overexpression of OTULIN in a rat model of cerebral ischemia/reperfusion inhibits the activation of the NF‐κB signaling pathway, thereby improving microglial activation and neuroinflammation." (PMID 39169794, 2024). "Collectively, these data suggest that OTULIN plays a direct role in the activation of microglial cells in focal cerebral ischemia/reperfusion rats." (PMID 29544517, 2018). "To analyze the time course of OTULIN expression following cerebral ischemia/reperfusion, we detected the levels of OTULIN mRNA and protein in the ischemic penumbra of the cerebral cortex within 72 h after reperfusion by Western blot and qRT-PCR." (PMID 29544517, 2018). "Together, these results suggest that cerebral ischemia induced an endogenous increase in OTULIN expression in the ischemic penumbra of the cerebral cortex." (PMID 29544517, 2018). "In the tMCAO rats, the focal cerebral ischemia/reperfusion injury induced a continuous increase in OTULIN expression within 72 h, and OTULIN expression was increased in activated microglial cells." (PMID 29544517, 2018). "Here, for the first time, we have revealed that the overexpression of OTULIN ameliorated microglial cell activation and neuroinflammation by repressing the NF-κB pathway in cerebral ischemia/reperfusion rats." (PMID 29544517, 2018). "Using an immunofluorescence approach, we observed that cerebral ischemia-induced OTULIN expression in activated microglia with an amoeboid shape, whereas OTULIN expression was low in the ramified microglia." (PMID 29544517, 2018). "Moreover, OTULIN overexpression has been reported to inhibit the NF‐κB pathway in a rat model of cerebral ischemia/reperfusion, improving microglial activation and neuroinflammation." (PMID 39169794, 2024).
Hepatitis (2 papers, 2020 to 2025). Inflammation of the liver. "Similarly, liver-specific deletion of OTULIN in mice leads to neonatally onset steatosis and hepatitis, akin to the ORAS patient." (PMID 32231246, 2020).
ischaemia (2 papers, 2018 to 2021). "As expected, OTULIN overexpression obviously alleviated ischemia-induced early brain damage as evidenced by reduced infarct volume, improved neurological function, and reduced neuronal loss in the ischemic penumbra." (PMID 29544517, 2018).
ischaemic stroke (2 papers, 2018 to 2021). "Overexpression of the OTULIN gene was utilized to observe the effect of OTULIN on ischemic stroke outcomes." (PMID 29544517, 2018). "Our data highlight the temporal and spatial distribution of OTULIN in the cerebral cortex following ischaemic stroke and revealed that enhanced OTULIN was required for EA to alleviate neuronal injury and activate glial cells, which was associated with the NF-κB signalling pathway." (PMID 33836646, 2021). "We previously demonstrated that enhanced OTULIN exerted a neuroprotective role in ischaemic stroke." (PMID 33836646, 2021). "Although there are still many unknown mechanisms, our results support OTULIN as a new target that exerts a neuroprotective role in ischaemic stroke." (PMID 33836646, 2021). "Collectively, these data indicate that the outcome of ischemic stroke could be improved by OTULIN overexpression." (PMID 29544517, 2018). "Hence, it was logical and valuable for us to assume that OTULIN played a protective role against ischemic stroke by modulating neuroinflammation." (PMID 29544517, 2018). "The endogenous OTULIN expression was rapidly and persistently increased in the ischemic penumbra of the cerebral cortex within 72 h following ischemic stroke, which indicates that rats may resist ischemic brain injury by mobilizing endogenous OTULIN." (PMID 29544517, 2018). "n summary, this study is the first to demonstrate that overexpression of OTULIN in an ischemic stroke model exerted a neuroprotective role via reduced infarct, improved neurological function deficits, and less neuronal loss in focal cerebral ischemia/reperfusion rats." (PMID 29544517, 2018). "Although further studies on the precise mechanism remain to be explored, we present the novel idea that OTULIN could be a promising candidate for the treatment of ischemic stroke." (PMID 29544517, 2018). "Initially, we examined the time course of OTULIN expression in the early stage of ischemic stroke." (PMID 29544517, 2018). "The present research showed, for the first time, that OTULIN was located primarily in neurons and microglia in a normal physiological state and following ischaemic stroke, but no OTULIN protein was detected in astrocytes." (PMID 33836646, 2021).
osteosarcoma (2 papers, 2024 to 2025). A usually aggressive malignant bone-forming mesenchymal neoplasm, predominantly affecting adolescents and young adults. "The results demonstrated that altering OTULIN expression alone did not alter the proliferative capacity of osteosarcoma cells but that OTULIN deficiency significantly reduced the resistance of osteosarcoma to cisplatin." (PMID 39721999, 2024). "Indeed, our data also revealed that OTULIN deficiency increases the sensitivity of osteosarcoma cells to apoptosis and necroptosis induced by cisplatin." (PMID 39721999, 2024). "We then investigated in vivo whether OTULIN is associated with cisplatin resistance in osteosarcoma cells." (PMID 39721999, 2024). "The electron microscopy results revealed that OTULIN deficiency promoted cisplatin-induced death in osteosarcoma cells, which exhibited a morphology closer to that of apoptotic cells and aggravated mitochondrial damage, including mitochondrial swelling and membrane rupture." (PMID 39721999, 2024). "This gene is homologous to OTULIN, which has been reported to interrupt the mitochondrial apoptotic pathway and induce cisplatin resistance in osteosarcoma." (PMID 40735324, 2025). "In contrast, the results of the wound healing assay demonstrated that compared with the control, OTULIN knockdown alone impeded the migratory capacity of osteosarcoma cells." (PMID 39721999, 2024). "To assess OTULIN expression in vitro, we treated six osteosarcoma cell lines (143B, U2OS, SAOS-2, HOS, KHOS and MG63) with different chemotherapeutic agents (cisplatin, doxorubicin, or methotrexate) for 24 h." (PMID 39721999, 2024). "To elucidate the mechanism by which OTULIN promotes resistance to apoptosis in osteosarcoma cells, we conducted immunoprecipitation (IP) analysis of 143B cells utilizing an anti-OTULIN-specific antibody (an anti-IgG antibody was used as a control)." (PMID 39721999, 2024). "In the present study, we found that OTULIN can act as a key molecule in promoting cisplatin resistance; this cisplatin-dependent upregulation of OTULIN expression markedly decreased the sensitivity of osteosarcoma cells to cisplatin-induced cell death." (PMID 39721999, 2024). "The CCK8 results also revealed that OTULIN knockdown significantly reduced the viability of osteosarcoma cells treated with erastin, whereas OTULIN overexpression increased the survival of osteosarcoma cells after erastin treatment." (PMID 39721999, 2024). "Moreover, we used RSL3, a known inducer of ferroptosis, to promote GPX4 degradation and found that the reduction in GPX4 levels in OTULIN-knockdown osteosarcoma cells was further accelerated by treatment with RSL3 together with CHX." (PMID 39721999, 2024). "Next, we collected tumor specimens from prechemotherapy and postchemotherapy osteosarcoma patients admitted to our hospital and found via immunohistochemistry that OTULIN expression was higher in postchemotherapy patients (n = 6) than in prechemotherapy patients (n = 6) with OS." (PMID 39721999, 2024). "Collectively, these findings indicate that GPX4 could be a downstream target of OTULIN that confers resistance to cisplatin in osteosarcoma by blocking the mitochondrial apoptotic pathway." (PMID 39721999, 2024). "However, OTULIN knockdown significantly enhanced the inhibitory effect of cisplatin on the invasive capacity of osteosarcoma cells." (PMID 39721999, 2024). "Furthermore, OTULIN knockdown enhanced the inhibitory effect of cisplatin on osteosarcoma cell migration." (PMID 39721999, 2024). "However, we provide novel evidence that OTULIN deficiency promotes the ubiquitination of GPX4, including linear ubiquitin and K48, in osteosarcoma cells, which promotes the proteasomal degradation of GPX4." (PMID 39721999, 2024). "Mechanistically, OTULIN maintains the stability of the GPX4 protein by regulating the ubiquitination level of GPX4, thereby conferring resistance to cisplatin in osteosarcoma cells." (PMID 39721999, 2024).
osteosarcoma (continued). "Taken together, our results indicate that OTULIN knockdown facilitates mitochondrial pathway apoptosis, but not ferroptosis, in cisplatin-treated osteosarcoma cells." (PMID 39721999, 2024). "In addition, our results also revealed that cisplatin did not significantly increase lipid peroxidation in osteosarcoma cells, with or without OTULIN knockdown." (PMID 39721999, 2024). "Moreover, the flow cytometry results revealed that the apoptosis rate of OTULIN-knockdown osteosarcoma cells after cisplatin intervention was reduced by Z-VAD-FMK, whereas that of fer-1-treated osteosarcoma cells was not." (PMID 39721999, 2024).
steatosis (2 papers, 2020 to 2022). Increased lipid within the cytoplasm of cells. "One ORAS patient carrying a homozygous missense mutation in OTULIN additionally suffered from steatosis and hepatocyte degeneration with abnormal liver values suggesting that functioning OTULIN is also essential for liver health." (PMID 35170849, 2022).
viral infection (2 papers, 2022 to 2025). "OTULIN is a linear deubiquitinase and a negative regulator of nuclear factor kB (NF-kB) signaling in the context of immunity and inflammation, and patients with OTULIN mutations are known to be susceptible to bacterial or viral infections." (PMID 36532050, 2022). "Taken together, OTULIN could be recruited by phosphorylated STING to remove the linear ubiquitin chains on STING at the late stage of virus infection, thus promoting lysosome‐mediated STING degradation to control antiviral immune responses against DNA virus." (PMID 40536345, 2025).
abscesses (1 paper, 2025). "Despite the degree of phenotypic heterogeneity seen in patients with OTULIN haploinsufficiency, the clinical course in the currently known patients demonstrates that the skin and lungs are particularly prone for the development of abscesses and necrosis." (PMID 41293556, 2025).
Alzheimer disease (1 paper, 2022). A progressive, neurodegenerative disease characterized by loss of function and death of nerve cells in several areas of the brain leading to loss of cognitive function such as memory and language. "In particular, we propose that loss of function mutations upstream of NF-κB such as ADAM17, SHARPIN, HOIL, or OTULIN affect NF-κB-activity in Alzheimer’s disease (AD) patients, in turn driving anatomical defects such as shrinkage of entorhinal cortex and the limbic system in early AD." (PMID 35983068, 2022).
autoimmune disease (1 paper, 2017). A disorder resulting from loss of function or tissue destruction of an organ or multiple organs, arising from humoral or cellular immune responses of the individual to their own tissue constituents. "Two independent groups reported that homozygous gene mutations of OTULIN/FAM105B were found in autoimmune disease patients." (PMID 28446710, 2017). "Gene mutations in HOIP, HOIL-1L and OTULIN are found in human patients who suffer from autoimmune diseases, and HOIL-1L mutations are also found in myopathy patients." (PMID 28446710, 2017).
breast tumors (1 paper, 2020). "We found that OTULIN is overexpressed in breast tumors, especially in the basal-like subtype." (PMID 32770022, 2020).